HMGB1 (high mobility group box 1)
Diseases named in the same sentence as HMGB1 in open-access papers (continued):
Sharing a sentence is not in itself a finding about the gene and the disease.
colon carcinoma (continued). "While one study reported that CARBO did not significantly increase ecto-CALR exposure and HMGB1 release in TSA cells (mouse mammary adenocarcinoma), another study reported its ability to induce ecto-CALR exposure and HMGB1 release in murine colon cancer cells." (PMID 32560232, 2020). "Conversely, elevated serum levels of HMGB1 were noted in cachexia than non-cachexia colon cancer patients, and exosomes generated by the CT26 colon cancer cells induced muscle wasting like phenotype in C2C12 myotubes and mice via the activation of TLR4-nuclear factor kappa B (NF-κB) pathway." (PMID 37355693, 2023).
Hyperglycemia (101 papers, 2011 to 2026). An increased concentration of glucose in the blood. "Among the inflammatory markers, hyperglycemia increases oxidative stress, causing endothelial and myocardial cell damage, which releases HMGB1." (PMID 40739795, 2025). "In this study, we explored the role of high mobility group box 1 (HMGB1) in hyperglycemia, a protein implicated in initiating inflammation and strongly correlated with DM onset and progression." (PMID 38187339, 2024). "In conclusion, our present study delivers the first direct evidence of a causal relationship between systemic HMGB1 knockdown and hyperglycemia in vivo, an association that had remained unexamined prior to this research." (PMID 38187339, 2024). "Our investigations aim to investigate the molecular pathways in which HMGB1 participates in modulating glucose control in hyperglycemia associated with DM." (PMID 38187339, 2024). "Prolonged hyperglycemia significantly promotes HMGB1 release, causing an upregulation of proinflammatory cytokines and increasing the expression of oxidative production and suppression." (PMID 37923892, 2023). "Some research studies suggest that hyperglycemia and insulin resistance underlying type 2 DM increase HMGB1 and RAGE expression both in diabetic mice and humans." (PMID 37373216, 2023). "Hyperglycemia has been implicated in increased HMGB1 expression in sensory neurons and endothelial cells." (PMID 32019145, 2020). "BecauseLGI is importantin the progression of both obesity and T2DM, we surmisedthat the underlying mechanism ofincreasing of hyperglycemia-induced HMGB1 expression was mainly related toinsulin resistance (IR)." (PMID 26317615, 2015). "On the basis of our findings, we propose a causal relationship linking hyperglycemia, activation of HMGB1/RAGE signaling axis, neuroinflammation, oxidative stress, and diabetic retinal neurodegeneration." (PMID 23766563, 2013). "Additionally, hyperglycemia stimulates the extracellular release of high mobility group box 1 (HMGB1), which functions as a damage-associated molecular pattern (DAMP) molecule." (PMID 41018477, 2025). "Thus, blocking HMGB1 signaling can help prevent complications associated with thrombolysis in ischemic stroke, especially in those with combined hyperglycemia." (PMID 38740617, 2025). "HMGB1, a proinflammatory cytokine, is elevated in DM associated hyperglycemia and inflammation." (PMID 38187339, 2024). "•The first in vivo study reveals causal association between HMGB1 and hyperglycemia." (PMID 38187339, 2024). "Although HMGB1 has been implicated in hyperglycaemia-induced heart problems, the fundamental mechanism still remains unclear." (PMID 37422477, 2023). "Hyperglycaemia has been shown to be associated with increased production of DAMPs such as HMGB1." (PMID 38983565, 2022). "Between the TLR ligands, High Mobility Group Box1 (HMGB1) has peculiar properties since modulating insulin resistance and insulin secretion, and it was positively associated with increased body mass index, insulin resistance, and hyperglycemia." (PMID 34360753, 2021). "In this study, the result of checking DNA damage caused by a hyperglycemia-induced ROS increase in the DM group confirmed the increase in oxidative DNA damage of salivary gland cells by oxidative stress through the increase in HMGB1 and 8-OHdG." (PMID 35056946, 2021). "HMGB1 induced by hyperglycemia may cause kidney damage in diabetic rats, and the pathogenic effect of HMGB1 may depend on the activation of RAGE and NF-κB." (PMID 33729484, 2021). "Oxidative stress and metabolic dysfunction, induced by hyperglycemia, directly lead to podocyte apoptosis, resulting in the release of podocyte-specific antigens and damage-associated molecular patterns (DAMPs), including high-mobility group box 1 (HMGB1) and ATP." (PMID 40534883, 2025).
Hyperglycemia (continued). "Taken together, these data suggest that rTMD1 confers general anti‐inflammatory, pro‐repair benefits and, in the diabetic cornea, specifically corrects hyperglycemia‐sensitive HMGB1/TLR4/NLRP3 signaling to facilitate reepithelialization." (PMID 41503166, 2026). "HMGB-1 was also strongly associated with NLRP3 inflammatory vesicle activation, which together amplified the risk of hyperglycemia-mediated hemorrhagic transformation." (PMID 38740617, 2025). "In the diabetic milieu, hyperglycemia promotes the release of HMGB1 and COX2 proteins, which exacerbate ROS formation intensifying the inflammatory cascade." (PMID 40173145, 2025). "To investigate the effect of HMGB1 knockdown on blood glucose levels and monitor the development of the hyperglycemia phenotype, we bi-weekly monitored fasting blood glucose levels in HMGB1 Flox and iHMGB1 KO mice after TMX and STZ administration." (PMID 38187339, 2024). "This discovery positions HMGB1 knockdown as a potentially efficacious therapeutic target for addressing hyperglycemia and, by extension, the DM epidemic." (PMID 38187339, 2024). "In conclusion, our current investigation stands as the first study to present compelling evidence that HMGB1 plays a pivotal role in regulating glucose metabolism, and that HMGB1 knockdown can significantly mitigate the severity of hyperglycemia in vivo." (PMID 38187339, 2024). "The breakthrough discovery in our current investigation was that systemic knockdown of HMGB1 in mice reduced the severity of hyperglycemia." (PMID 38187339, 2024). "While this model provided insight into the isolated role of HMGB1 in hyperglycemia, it oversimplifies the complex systemic nature of DM." (PMID 38187339, 2024). "Thirdly, our study design involved inducing HMGB1 knockdown before the onset of hyperglycemia, which limits the strength of evidence for HMGB1 as a therapeutic target in established DM." (PMID 38187339, 2024). "Its beneficial actions likely stem from reducing oxidative stress, dyslipidemia, and hyperglycemia, potentially through the modulation of HMGB1, SIRT1, and NF-kB pathways." (PMID 39432066, 2024). "We subsequently represented these genes of interest in a volcano plot and heatmap, respectively, providing visual representations of DEGs occurred as a result of systemic HMGB1 knockdown in the liver of hyperglycemia mice." (PMID 38187339, 2024). "Hyperglycemia induces renal autophagy and activates the HMGB1/NF-κB signal pathway, leading to the increase of inflammatory mediators, extracellular matrix (ECM) deposition, and proteinuria in the kidney." (PMID 38800022, 2024). "Hyperglycemia-mediated oxidative stress promotes the expression of HMGB1 and RAGE, which activate autophagy." (PMID 37065747, 2023). "Two previous studies, carried out in subjects with cystic fibrosis-related diabetes and in a lipopolysaccharide-induced septic rat model, respectively, have shown that HMGB1 was increased in the presence of hyperglycaemia and was lowered after insulin therapy." (PMID 37256493, 2023). "HMGB1 is synthesized and secreted by immune cells, and in response to hyperglycemia or other stressors, HMGB1 binds TLR4 and RAGE." (PMID 37065747, 2023). "MSC-derived Exos, which contain miRNA-126, can attenuate hyperglycemia-induced retinal inflammation by downregulating the expression of the high-mobility group box 1 (HMGB1)." (PMID 36969177, 2023). "Accumulating evidence has demonstrated that hypoxia, reactive oxygen, nitrogen species, hyperglycemia, cytokines TNFα, and INFγ induce tumor cells to actively secrete HMGB1 into the extracellular matrix." (PMID 38003396, 2023). "Hyperglycemia-mediated oxidative stress promotes the expression of HMGB1 and RAGE, thereby activating autophagy." (PMID 37065747, 2023). "Microglial matrix metalloproteinase 9 (MMP-9) levels are raised in response to hyperglycaemia via HMGB1/TLR4 signalling in BV2 murine glial cells." (PMID 38983565, 2022).
Hyperglycemia (continued). "Hyperglycaemia (HG) exacerbates myocardial ischaemia/reperfusion (I/R) injury with the activation of HMGB1‐RAGE/TLR2/TLR4‐NF‐κB signalling, which is reversed by ethyl pyruvate (EP) treatment." (PMID 35706377, 2022). "Human umbilical cord mesenchymal stem cell-derived exosomes carried overexpressing miR-126 alleviate the hyperglycemia-induced inflammation by reducing HMGB1 in human retinal ECs." (PMID 36376958, 2022). "Cellular stress causes the generation of RAGE ligands such as high mobility group box 1 (HMGB1) protein, S100 proteins, and nucleic acids, while prolonged hyperglycemia and inflammation induce the release of the ligands AGE and amyloid." (PMID 33776579, 2021). "Previous studies have indicated that MSC-Exo-derived miR-126 can suppress hyperglycemia-induced inflammation by down-regulating high mobility group box-1 (HMGB1) protein, which can bind to TLR2, TLR4, and inflammasomes then help activate the NLRP3 pathway." (PMID 35047512, 2021). "Upregulated expression of DNA-binding nuclear protein HMGB1, along with changes in histone methylation marker H3K9me1 have demonstrated hyperglycemia-induced damage to cardiomyocyte at 24 h of exposure." (PMID 34639171, 2021). "The role of HMGB1 as a mediator in the secretion of pro-inflammatory cytokines after different stimuli such as hyperglycemia has already been reported in SV40 MES 13 cells by activating the NF-κB pathways." (PMID 34360753, 2021). "A linear relationship has been consistently observed among HMGB1 levels and inflammation, IR, and hyperglycemia." (PMID 33912566, 2021). "Many studies have demonstrated that DM, and then hyperglycemia, upregulate the expression of and increase in the levels of HMGB1." (PMID 32722545, 2020). "Chromatin immunoprecipitation (ChIP) analyses indicated that hyperglycemia significantly increased the levels of H3K9ac at the promoter region of HMGB1 in the dorsal horn of diabetic animals as compared with the control animals." (PMID 32019145, 2020). "HMGB1 is also upregulated by hyperglycemia and appears to play a major role in lung inflammation especially in the context of DM." (PMID 32760352, 2020). "Immunohistochemical studies revealed that hyperglycemia mediated inflammation influenced HMGB1 acetylation and its release from the neurons." (PMID 32019145, 2020). "This unique study also confirmed that, irrespective of Type 2 diabetic rat or mice model as well as hyperglycemic cell culture model, hyperglycemia increased the expression of HMGB1 and H3K9ac with alterations in inflammatory mediators." (PMID 32019145, 2020). "The results of ChIP analyses further confirmed the hyperglycemia mediated increased acetylation of H3K9 and its association to the HMGB1 promoter that up-regulated HMGB1 expression in spinal dorsal horn of ZDF animals six to eight weeks after hyperglycemia." (PMID 32019145, 2020). "Some studies have described differential effects of HMGB1-dependent signaling on hyperglycemia-induced complications." (PMID 31165005, 2019). "In mice with diabetic cardiomyopathy, high mobility group box 1 protein (HMGB1) mediates hyperglycemia-induced cardiomyocyte apoptosis via ERK/c-Ets-1 signaling pathway." (PMID 31025089, 2019). "In vitro and in vivo, hyperglycemia induces HMGB1 RNA expression and it increases HMGB1 protein levels in myocardial cells and fibroblasts." (PMID 31835864, 2019). "The relationship between HMGB1 and neuropathic changes induced by hyperglycemia has been evaluated even in retinal neuropathy." (PMID 31835864, 2019). "BMP2 is upregulated by hyperglycaemia, activating the ligand high mobility group box 1 (HMGB1), which translocates to the nucleus, binding to a cAMP response element (CRE) region of the BMP2 promoter, inducing its expression." (PMID 30619890, 2018). "A study has proven that hyperglycemia accelerates the release of HMGB1 and RAGE in human aortic endothelial cells." (PMID 29054968, 2017).
Hyperglycemia (continued). "Hyperglycemia enhances extracellular release of HMGB1, which has been demonstrated as an important mechanism for worsened ischemic damage." (PMID 28152042, 2017). "They indicated that hyperglycemia augments the early secretion of HMGB1 from ischemic brain tissue, which led to increased infarct volume, neurological deficit, cerebral edema, and BBB disruption." (PMID 29054968, 2017). "An in vitro experiment showed that metformin protected hyperglycemia-induced cardiomyocytes injury via inhibition of HMGB-1/RAGE expression." (PMID 27847406, 2016). "We are unaware of any studies on the miRNA regulation of HMGB1 levels in hyperglycemia and diabetic retinopathy." (PMID 26997759, 2016). "Our results suggest that miR-146a decreases the levels of hyperglycemia-induced TNFα possibly through the inhibition of HMGB1, TLR4, MyD88, and TRIF/IRF3 signaling." (PMID 26997759, 2016). "In the present study, we demonstrated that overexpression of miR-146a induced the decrease of HMGB1 levels in REC in hyperglycemia." (PMID 26997759, 2016). "More and more investigations indicated that HMGB-1 was diffusely expressed in myocardium of diabetic mice and in hyperglycemia-induced cardiomyocytes." (PMID 27847406, 2016). "This is in accordance with previous reports that hyperglycemia induced HMGB-1 expression in endothelial cells, vascular smooth muscle cells, and cardiomyocytes." (PMID 26798412, 2016). "HMGB1 inhibition effectively ameliorated hyperglycaemia-activated caspase-3 (P < 0.05) and decreased Bax/Bcl-2 ratio (P < 0.05)." (PMID 25210949, 2014). "Findings from this study reveal that on admission to ICU, critically ill patients with hyperglycemia display elevated circulating levels of sRAGE, HMGB-1 and soluble thrombomodulin." (PMID 21871056, 2011). "Increased vascular HMGB1 expression was demonstrated in diabetic animals, and recently it was demonstrated that hyperglycemia-induced reactive oxygen species production increases the expression of HMGB1 and RAGE in endothelial cells." (PMID 21365018, 2011). "Hyperglycemia, a hallmark of diabetes, was shown to upregulate HMGB1 activity in HFpEF-DM patients compared to the non-DM group." (PMID 40369521, 2025). "Hyperglycemia activates the HMGB1-RAGE signaling pathway and induces the release of inflammatory factors and neutrophil infiltration, given that Xiao-Xu-Ming decoction inhibits RAGE-mediated neuroinflammation, blood–brain barrier disruption, and hemorrhagic transformation." (PMID 38740617, 2025). "Under hyperglycemia, inflammatory mediators such as high mobility group box‐1 protein (HMGB1), platelet‐derived growth factor (PDGF), phenylacetylglutamine (PAGln), lysophosphatidic acid (LPA), and citrullinated histone H3 (CH3) are upregulated, yet research on their specific roles remains limited." (PMID 40739795, 2025). "Hyperglycemia is the main cause of BBB damage and can induce oxidative stress, inflammatory response, Advanced glycation end products (AGEs) accumulation, and high-mobility group box 1 (HMGB1) signaling axis activation." (PMID 40540715, 2025). "High-mobility group box 1 (HMGB1) levels and inflammasome activities in human retinal ECs were demonstrated to be suppressed by exosomes obtained from miR-126-transfected MSCs under the effect of hyperglycemia." (PMID 38632264, 2024). "•HMGB1 knockdown presents as a potent therapeutic target for hyperglycemia in DM." (PMID 38187339, 2024). "Silencing of High-mobility group box 1 protein (HMGB1) might protect against hyperglycemia-induced cardiomyocyte apoptosis by inhibiting ERK-related signaling pathway." (PMID 38308007, 2024). "It was reported that hyperglycemia-induced HMGB1 release could induce and stimulate renal injury in diabetic rats." (PMID 37498374, 2024). "We hypothesized that HMGB1 knockdown will mitigate hyperglycemia severity and enhance glucose tolerance." (PMID 38187339, 2024).